CXCL8 (C-X-C motif chemokine ligand 8)
Diseases named in the same sentence as CXCL8 in open-access papers (continued):
Sharing a sentence is not in itself a finding about the gene and the disease.
cancer (continued). "NF-κB in cancer cells promotes angiogenesis by increasing the expression of C-X-C motif chemokine receptor 4 (CXCR4) and CXCL8/interleukin-8 (IL-8)." (PMID 40597301, 2025). "Transcriptomic analysis of the microdissected tumors (GSE164665) revealed higher expression of CXCR2, a known receptor for CXCL8, in stromal cells, whereas SLC6A14 was predominantly expressed in cancer cells." (PMID 41444422, 2025). "The specific fusion protein under examination, hsa/mtCXCL8, emerges as highly promising for applications in conditions where the CXCL8–GAG interaction plays a pivotal role in pathology, such as in chronic inflammation and cancer." (PMID 40124384, 2025). "In agreement with our experimental data and the HMS LINCS analysis, we found that CXCL8 expression is strongly correlated with CXCL1 (R2 = 0.59), followed by CXCL2 (R2 = 0.49) and CXCL3 (R2 = 0.48), across all DepMap cancer cell lines." (PMID 40833805, 2025). "Key molecules for cancer progression were inhibited (IL6, IL4, CXCL8, CXCR4, CXCL12; ICAM1, CD44 and BCL2), and pro-apoptotic BAD was activated." (PMID 41595551, 2025). "IL-6 and IL-8 (CXCL8) are well-known classical SASP factors, but even their expression and levels vary depending on the cancer type and type of senescence inducer." (PMID 41264145, 2025). "Our findings confirm the involvement of the CXCL8/CXCR2-axis in promoting pro-tumorigenic effects in TC cells, further demonstrating its immunotherapeutic significance in human cancer." (PMID 38900374, 2025). "Heatmap analyses revealed that GPATCH3 expression was broadly negatively correlated with chemokines such as CXCL5 and CXCL8, as well as immunostimulatory molecules including CD40LG and TNFSF15, in a pan-cancer context." (PMID 40861452, 2025). "This pathway enhances the expression of interleukin‐8 (CXCL8) and VEGF, which promotes key cancer hallmarks, including angiogenesis and metastasis." (PMID 40969301, 2025). "In the context of cancer, their recruitment is largely driven by chemokines such as CXCL1, CXCL2(IL-2), and CXCL8(IL-8), which are often upregulated in the TME." (PMID 40486614, 2025). "A significant upregulation of CXCL8 was observed in response to both iMSC- and WJMSC-derived Exos in both cancer cell lines." (PMID 40649957, 2025). "It was demonstrated that cancer cells exhibited elevated expression of the ligands CXCL1, CXCL2, CXCL3, and CXCL8, which mediate signaling through the receptors CXCR1 and CXCR2 on TANs." (PMID 41254689, 2025). "Complementary qRT-PCR analysis demonstrated significant transcriptional upregulation of oncogenic effectors - EFNA1, CXCL8, and PPP1R14A in carcinoma versus control tissues (P<0.05)." (PMID 40406253, 2025). "TCGA database indicated that among several ligands, CXCL1, CXCL3, CXCL5, CXCL7 and CXCL8 (ligands for CXCR2) and CCL15 (ligand for CCR1) were particularly upregulated in CRC tissues compared with other cancers." (PMID 38750114, 2024). "CXCL8 has been reported to induce release of VEGF and MMP-2, which are involved in metastasis-related tissue remodeling, along with the progression and cancer metastasis." (PMID 38213742, 2024). "PeCa cells release CXCL8, DKK1, and CD147, leading to reprogrammed fibroblasts and TAN promoting cancer progression and metastasis." (PMID 39333233, 2024). "We identified several potential CHI3L1 target proteins, including VEGFA, TGF-β1, Cluster of Differentiation 74 (CD74), IL-6, inhibitor of DNA binding 3 (ID3), MMP9, CXCL8, and SPP1, in this type of cancer." (PMID 38177294, 2024). "Treg cells producing C-X-C Motif Chemokine Ligand 8 (CXCL8) and IL-17 not only suppress T cells but also promote inflammation within the cancer microenvironment." (PMID 39136031, 2024). "We selected eight candidates (CST4, CCL20, CX3CL1, CXCL5, CXCL8, GDF15, CCL5 and MMP3) that play an important role in cancer pathogenesis for further study." (PMID 38385965, 2024).
cancer (continued). "Despite contradictory reports, high CXCL1, CXCL2, CXCL8, CXCR2 levels and accordingly high neutrophil levels correlate with cancer aggressiveness and poor patient survival in general." (PMID 38786066, 2024). "They found that the chemokines CXCL8 and CXCL5 were up-regulated in high-grade sinonasal cancer, affecting leukocyte activation and trafficking, angiogenesis, metastasis and cancer cell proliferation." (PMID 39097562, 2024). "Given that anti‐CXCL8 and anti‐CXCR1/2 drugs are in advanced stages of clinical development for the treatment of cancers and other diseases, combinatorial therapies involving these drugs and clinically available anti‐EGFR drugs are a real possibility." (PMID 38757578, 2024). "Dex-treatment leads to the destabilization of ARE-containing mRNAs of TNF and CXCL8, and PTGS2 in cancer cells." (PMID 38195703, 2024). "By interfering with CXCL8, CXCR1/2 activates variable signaling pathways in cancer cells, including the RAS–RAF–MEK–ERK and PI3K–AKT–mTOR pathways." (PMID 38756650, 2024). "As a result, CA-MSCs secrete immune cell suppressor molecules and chemokines such as ICAM-I, PD-L1, VCAM, HLA-G, COX-2, IDO, TGF-β, PGE2, CXCL11, CXCL8, CXCL9, CXCL6, CXCL10, CXCL1, and promote cancer cells viability and increase their growth." (PMID 38022534, 2023). "Transcriptome analysis revealed that CHRM3 knockdown significantly reduced an array of classic factors involved in cancer invasive growth, including MMP1/MMP3/MMP10/MMP12 and CXCL1/CXCL5/CXCL8." (PMID 37744266, 2023). "PDCD1, TGFB1, CXCL8, CCL3, CCL4, and CCL5 were highly expressed in subTME-IS; CXCL2 and CXCL12 were highly expressed in subTME-ICI, which was consistent among cancer types." (PMID 38002057, 2023). "Surprisingly, the cancer cell line encyclopedia (CCLE) dataset revealed that H2228 cells also expressed elevated mRNA levels of IL-1α and CXCL8 (downstream target of IL-1 signaling)." (PMID 37985999, 2023). "Transcriptome analysis revealed that CHRM3 knockdown significantly reduced an array of classic factors in cancer invasive growth including MMP1/MMP3/MMP10/MMP12 and CXCL1/CXCL5/CXCL8." (PMID 37744266, 2023). "VEGFR1 causes an increase in B-cell leukemia/lymphoma-2 (Bcl-2) expression in cancer cells; this protein activates nuclear factor κB (NF-κB), the transcription factor responsible for the increase in CXCL1 expression, as well as CXCL8." (PMID 37408240, 2023). "CXCL1 expression occurs in cancer cells, and CXCL1 and CXCL8 expression occurs in HCC cancer stem cells." (PMID 37408240, 2023). "However, CXCL8 and other key neutrophil chemoattractants can be produced by cancer cells as well as a variety of stroma and immune cells, notably neutrophils and other myeloid cells themselves, and its predominant source may change over the course of transformation." (PMID 37192000, 2023). "The chemokine CXCL8 (also known as interleukin-8, abbreviated IL-8) and its G-protein-coupled receptors CXCR1 and CXCR2 are crucial elements in this process, and also the development of many cancers." (PMID 37433790, 2023). "Cancer cells express various cytokines, chemokines, and growth factors such as IL-6, CCL2, CXCL8, CSF1, and CSF2, which impact vascular permeability, lymph angiogenesis, and metastasis." (PMID 37894465, 2023). "The CCL2/CCR2 and CXCL8/CXCR2 axes play an essential role in the malignant progression of tumors and act as novel targets for cancer treatment." (PMID 36403057, 2022). "Pro-tumor chemokines, such as CXCL8, CXCL9, CXCL10, and CXCL11, can promote cancer cell proliferation and metastasis, and our results revealed that NEIL3 expression was positively correlated with them." (PMID 36612106, 2022). "Among those downregulated, CXCL1, CCL2, CXCL8, CTGF, LIF, and IL-6 are known to be involved in fibrosis or cancer stroma." (PMID 36289649, 2022). "Interleukin-8 (IL-8, also called CXCL8) is a cytokine of the CXC chemokine family that is believed to be related to cancer development and chronic inflammation." (PMID 35045833, 2022).
cancer (continued). "Among these, inflammatory cytokine CXCL8 and its receptor CXCR1/2 axis have a confirmed regulatory role in pro-inflammation, cancer cell multiplication, invasion and metastasis." (PMID 35922850, 2022). "CXCL8 can recruit neutrophils and MDSC around cancer cells to form neutrophil extracellular traps (NETs) and protect them from cytotoxicity mediated by CD8+ T cells and natural kill (NK) cells, which in turn affects the efficacy of ICIs therapy." (PMID 36358719, 2022). "Recently, increased studies evidence that CXCL8 can induce the activation of Janus kinases and signal transducer and activator of transcription protein 3 (JAK/STAT3) signaling in both cancer and immune cells." (PMID 35372515, 2022). "Interleukin-8 (IL-8/CXCL8) is a pro-angiogenic and pro-inflammatory chemokine that plays a role in cancer development." (PMID 36522309, 2022). "Another study has shown that CXCL8 induces the production of NETs through communicating with CXCR2, which, in turn, promotes cancer cell proliferation and migration." (PMID 36091114, 2022). "CXCL8 and CCL2 are two chemokines playing important roles in driving the progression of different types of cancer." (PMID 35498406, 2022). "In luminal A cancer subgroup, the combined parameter analysis showed the highest SE (76.74%), SV (37.50%), PPV (56.9%) and NPV (60%) for the CXCL8 + CA 15-3 combination, reaching the highest SE and NPV values shown in the entire study." (PMID 36431173, 2022). "Nevertheless, hypoxic cancer-derived EVs have been shown to be enriched in factors known to play a role in neutrophil chemotaxis, including CXCL8 (IL-8) and MIR-451." (PMID 36010994, 2022). "For example, cisplatin triggers the expression of multiple cytokines including IL-6, CCL2, CCL5, CXCL8, BFGF, G-CSF, and VEGF in cancer cells or stromal cells of TME." (PMID 35784460, 2022). "Although the mean expression levels of IL6, CXCL8, IL10, and IL17A were higher in the cancer group than those in the control group, the difference was not statistically significant." (PMID 36501012, 2022). "PADI4 inhibitor treatment in cancer cells downregulated four genes related to metastatic cancer phenotypes: Laminin Subunit Gamma 2 (LAMC2), C-X-C Motif Chemokine Ligand 8 (CXCL8), Niban Apoptosis Regulator 1 (FAM129A), and Pleckstrin 2 (PLEK2)." (PMID 36233212, 2022). "Out of the detected hub genes, six (CCL20, CXCL1, CXCL3, CXCL8, CXCL11, and MMP1) were among over-expressed vDEGs which have been corroborated by the GEPIA in both COAD and READ cancer types." (PMID 35333898, 2022). "In other cancer types (e.g., prostate cancer) adipose stromal cells can migrate to tumors in response to the production of chemokines (CXCL1 and CXCL8)." (PMID 33557173, 2021). "For example, chemokines, including CXCL6 and CXCL8, are one of the many secreted mediators that are upregulated in a Snail-dependent manner when EMT pathways are activated in cancer cells by EGF or TGF-β treatment." (PMID 34567000, 2021). "Cytokine secretion is variable depending on cancer type, but generally involves IL-1, IL-6, CXCL8/IL-8, IL-10, and interferon-gamma." (PMID 33763351, 2021). "Here, we report that under acute ER stress C/EBPδ is induced by the PERK pathway to contribute to the induction of the chemokines CXCL8 and CCL20, thus revealing a novel mechanism for ER stress-mediated modulation of cancer cells’ microenvironment." (PMID 34725321, 2021). "Thus, CXCL8 may be a potential monitoring and prognostic marker in HCV-related HCC, and in the assessment of patients at increased risk of HCC development regulated by HCV and cancer-promoting genes." (PMID 34680563, 2021). "The aim of our study was to evaluate the usefulness of serum CXCL8 and CXCR2 concentrations as biomarkers in the diagnosis and progression of this cancer." (PMID 34680333, 2021). "BCL2, CXCL8, and FGF1 promote cancer cell metastasis and invasion through EMT regulation in various cancers." (PMID 34199510, 2021).
cancer (continued). "It is suggested that selected chemokines such as CXCL8 and its specific receptor CXCR2 are involved in cancer progression, including GC." (PMID 34680333, 2021). "In this cancer, hypoxia increases the expression of angiogenic factors such as VEGF, CXCL8 and CXCL12." (PMID 33467722, 2021). "Trabectedin and lurbinectedin also reduce the production of growth factors, angiogenic and pro-inflammatory mediators such as CCL2, IL-6, CXCL8, MIF, and IL-6 in cancer cells, monocytes, and TAMs." (PMID 33026575, 2021). "Studies have shown that CXCL8 directly contributes to TME remodeling, cancer plasticity, and the development of resistance to both chemotherapy and immunotherapy." (PMID 35011369, 2021). "During cancer progression, cancer cell-derived CCL2, CCL5, CXCL8, and CXCL5 are released and recruit immunosuppressive-myeloid cells into the TME, including MDSCs, TAMs, and TANs through CXCR2 activation." (PMID 35127700, 2021). "Cancer cells expressed high levels of ligands CXCL1, CXCL2, CXCL3, and CXCL8, signaling to the receptors CXCR1 and CXCR2 expressed by neutrophils." (PMID 33953163, 2021). "The interaction between CXCL8 and CXCR1/2 regulates the trafficking of cells for cancer progression in the TME." (PMID 34025668, 2021). "CXCL10, CXCL8, CXCL2, and CXCL3 can also induce cell growth and proliferation and are putative autocrine or paracrine growth factors in cancer." (PMID 33939688, 2021). "In our pan-cancer analysis, we found a strong and significant correlation between inflammatory (IL6, CXCL8, IL12, TGFβ) and suppressive cytokines (IL10) with EMT score." (PMID 35096592, 2021). "In particular, CXCL8 is increased in inflammation, while CRC is increased through CXCR1 and is involved in cells transition from normal to carcinoma." (PMID 34944856, 2021). "CXCL8 and its related ELR+ CXC chemokines are a major regulator of neutrophil migration but they have also diverse impacts on multiple aspects of cancer cells, including their proliferation, survival and migration." (PMID 32422991, 2020). "Bioinformatic analyses, performed to assess the role of 41 cytokines after RT exposure and their network interactions, suggested TGF-β, MIF, CCL2, CXCL5, CXCL8 and CXCL12 as master regulators of cancer immune escape in RMS tumors." (PMID 32854690, 2020). "ACKR3 expression at the protein level was elevated in aggressive prostate tumors, where ACKR3 can increase the expression of pro-angiogenic factors such as CXCL8 and VEGF and support the transendothelial migration of cancer cells." (PMID 32456359, 2020). "After assessing the diagnosis and prognostic values of identified key regulators in both the TCGA and GEO verification datasets, CXCL8, CYP2C8, and E2F1 were selected, which were reported as potential biomarkers in some cancers." (PMID 32851080, 2020). "These macrophages show the expression of the M2 polarization marker CD206, as well as the expression of cytokines that are important in the progression of cancer: IL-10, CXCL8/IL-8 and CCL2/MCP-1." (PMID 33114763, 2020). "As expected, cancer cluster-related genes ATF3, PDZK1, VTN and CXCL8 were highly expressed in CDRCC tissues, and patients with high expression of these genes had significantly poor prognosis (P<0.01)." (PMID 33162821, 2020). "While CCL14 and XCL1 have shown only good prognostic value, other chemokines such as CCL5, CCL20/CCR6, CCR7, CXCL1, CXCL8, and CXCL12/CXCR4 have consistently played the role of poor prognostic markers in different kinds of cancer." (PMID 31991604, 2020). "Cinobufacin injection plays an important role in the treatment of malignant tumors by regulating the expression of AKT1, VEFG, EGFR, CASP3, and CXCL8." (PMID 32148531, 2020). "We found that both HIF‐1α and HIF‐2α (EPAS1) have the ability to activate oncogenes deeply involved in cancer biology, such as VEGF, CXCL8 and PGR." (PMID 32537867, 2020).
cancer (continued). "After traversing BBB, cancer cells secrete various cytokines, chemokines, and mediators, particularly IL-1β, TNF-α, IFN-γ, CCL2, CXCL8, and COX2." (PMID 31900168, 2020). "CXCL8, a member of CXC chemokines, was constitutively expressed in many types of human cancers, and its overexpression has been shown to play a critical role in promoting tumorigenesis." (PMID 32766720, 2020). "For example, peri-tumor tissue-sourced fibroblasts secrete various cytokines, including IL-6, CXCL1, CCL2, SCGF-β, CXCL8 and HGF, to recruit cancer stem cells, maintain cancer stemness and promote intrahepatic metastasis of HCC." (PMID 30999932, 2019). "CXCL8 also upregulates CXCR7/ACKR3, which is involved in stemness features of cancer cells suggesting it is also likely involved in EPC mobilization." (PMID 30800123, 2019). "Previous studies have demonstrated that CXCL8 and CXCL7 regulated the progression of various cancers via binding to CXCR1 and CXCR2." (PMID 30984000, 2019). "Several of these pro-inflammatory chemokines such as CXCL1, CXCL8 and CXCL12 drive cancer progression by facilitating cell growth, survival and migration and inducing angiogenesis." (PMID 29719625, 2018). "In several cancer cell lines, it was demonstrated that the activation of MAPK by CXCL8 results in increased cell proliferation and survival." (PMID 29977225, 2018). "PMNs activated by a TC-CM are a major source of several protumorigenic and angiogenic factors (i.e. VEGF-A, CXCL8/IL-8, and MMP-9) which are known players in cancer-related inflammation." (PMID 29953504, 2018). "One of our top hits, IL-8, also known as C-X-C motif ligand 8 (CXCL8), is a pro-inflammatory chemokine with known roles in promoting cancer cell invasion." (PMID 30458137, 2018). "Interleukin‐8 (IL‐8 or called CXCL8), a cytokine of the CXC chemokine family, has been proposed to contribute to chronic inflammation and cancer development." (PMID 26945908, 2016). "Interleukin-8 (IL-8, CXCL8) is one of the CXC chemokines, which plays multiple roles in immune response and cancer." (PMID 27076368, 2016). "In conclusion, our data identify anti-IGF-1R monoclonal antibody-induced cancer–stromal cell communication via STAT3-dependent IGF-2 production in cancer cells and a positive IGF-2/CXCL8 feedback loop through the intercellular IGF-2/IGF-2R system." (PMID 26465273, 2015). "CXCL8, also known as IL-8, is a type of CXC chemokine involved in angiogenesis, which is important for tumorigenesis, cancer progression, and metastasis." (PMID 26649771, 2015). "As an angiogenic chemokine, CXCL8 binds with high affinity to both the CXCR1 and CXCR2 receptors, contributing to its function in the cancer microenvironment." (PMID 24224100, 2013). "In this way, our observation of the fast up-regulation of CXCL8, CXCL6 and CXCL1 by 1,25(OH)2D3 provides an additional aspect to the effects of the nuclear hormone on the immune response with impact on cancer immunology." (PMID 24250750, 2013). "It has been shown that matrix metalloproteinase-1 (MMP-1) causes activation of PAR1 leading to expression of the pro-angiogenic secreted chemokines CXCL8 (IL-8), CXCL1 (GRO-α), and CCL2 (MCP-1) by the cancer cells." (PMID 24384839, 2013). "Their cytotoxicity and potential anti-inflammatory and anti-cancer activities are reported in terms of effects on NO, the cytokines IL-1, TNF-α and chemokine CXCL-8 (IL-8) production relative to the naturally occurring curcumin." (PMID 23353121, 2013). "For the sake of simplicity, in the following sections of the manuscript the four chemokines (CCL2, CCL5, CXCL8, CXCL10) will be referred together as “cancer-related chemokine cluster”." (PMID 24213226, 2012). "These cells were exposed to microenvironmental pressures, and the expression of a cancer-related chemokine cluster was used as readout for the malignancy potential (CCL2, CCL5, CXCL8, CXCL10)." (PMID 24213226, 2012).